FASN (fatty acid synthase)
Diseases named in the same sentence as FASN in open-access papers (continued):
Sharing a sentence is not in itself a finding about the gene and the disease.
hepatocellular carcinoma (continued). "All hepatoma cells analyzed responded to the LXRα agonist T0901317 by inducing fatty acid synthase (FASN) expression." (PMID 31097694, 2019). "For this purpose, FASN expression was modulated in human hepatoma cell lines and protein levels of c-Met were assessed." (PMID 26857837, 2016). "A cerulenin/paclitaxel combination significantly inhibited growth in FASN-overexpressing, paclitaxel-resistant hepatocellular carcinoma cells." (PMID 25947066, 2015). "Elsewhere, stronger FASN expression was described in a paclitaxel-resistant hepatocellular carcinoma cell line, Hep3B, than in its paclitaxel-sensitive parental clone." (PMID 25947066, 2015). "In brain tumors and hepatocellular carcinoma, it has been also reported that FASN is highly expressed and FASN inhibition is effective to reduce cell proliferation and that radiolabeled acetate uptake is associated with the fatty acid synthesis." (PMID 23741342, 2013). "In our previous study, an autoantibody related to hepatocellular carcinoma was identified, of which specific target was fatty acid synthase (FASN) with a molecular weight of ∼200 kDa." (PMID 23128437, 2013). "It was found that PTBP1 regulates lipid metabolism in hepatocellular carcinoma cells and thus inhibits oxidative stress and promotes hepatocellular carcinoma development by promoting the transport of the key gene for fatty acid synthesis, FASN mRNA, into the cytoplasm to facilitate its translation." (PMID 40579921, 2025). "Furthermore, the suppression of RTKs/PI3K/Akt/mTORC1/SREBP1 axis was also identified as a pathway by which EGCG downregulates FASN expression in hepatoma cells." (PMID 38348027, 2024). "Moreover, EGCG was found to inhibit mTOR signaling and downregulate FASN expression by stimulating AMPK expression in hepatoma cells." (PMID 38348027, 2024). "In addition, ACSS2 induced histone acetylation at the FASN promoter region, which upregulated FASN expression to enhance lipid synthesis to promote the survival of hepatocellular carcinoma." (PMID 38060103, 2023). "Therefore, we selected hepatocellular carcinoma (with relatively high FASN expression) to investigate the inhibitory effect of mir-195-5p in tumors for the next study." (PMID 36555243, 2022). "In this study, we describe that naturally occurring isothiocyanate sulforaphane (SFaN) impairs fatty acid synthase promoter activity and reduces SREBP target gene (e.g., fatty acid synthase and acetyl-CoA carboxylase 1) expression in human hepatoma Huh-7 cells." (PMID 35610278, 2022). "Finally, mir-195-5p capable of disrupting FASN function in hepatocellular carcinoma has been identified." (PMID 36555243, 2022). "Additionally, overexpression of myristoylated Akt increased USP2-1 expression in hepatoma, which was accompanied by high levels of expression of lipogenic proteins including FASN, acetyl-CoA carboxylase, and adenosine triphosphate citrate lyase." (PMID 33530560, 2021). "A similar result was obtained using the hepatoma cell line, where there was upregulation of FASN." (PMID 34552769, 2021). "However, elevated levels of deacetylated FASN have also been detected in hepatocellular carcinoma and this has been attributed to HDAC3 activity." (PMID 32872164, 2020). "In a mouse hepatoma model, metformin decreased de novo fatty acid synthesis by reducing, transcriptionally, the expression of acetyl CoA carboxylase, fatty acid synthase (FASN) and ATP citrate lyase (ACLY)." (PMID 33182253, 2020). "A previous study showed down-regulating TIP30 activated the Akt/mTOR signaling pathway to up-regulate SREBP1 expression, which promoted lipid metabolism by activating gene transcription of lipogenesis, including FASN and SC, promoting proliferation of hepatocellular cancer cells." (PMID 31299935, 2019).
hepatocellular carcinoma (continued). "In addition, EGCG generates the AMPK expression that results in the inhibition of mTORC1/SREBP1 axis expression, leading to decreased FASN expression in human hepatoma cells." (PMID 29588626, 2018). "Metabolically, palmitate supplied by FASN inhibits hepatocellular carcinoma (HCC) metastasis through CD44 lipid raft sequestration." (PMID 40626019, 2025). "Background and Objectives: Aberrant upregulation of fatty acid synthase (FASN), catalyzing de novo synthesis of fatty acids, occurs in various tumor types, including human hepatocellular carcinoma (HCC)." (PMID 39064589, 2024). "Accordingly, genetic or pharmacological inhibition of FASN has been found to increase MHC-I (also called HLA-I) levels in hepatocellular carcinoma (HCC), promoting antigen presentation and stimulating antigen-specific CD8 + T-cell cytotoxicity." (PMID 39349429, 2024). "TRIM21 inhibits fatty acid (FA) synthesis by ubiquitination and degradation of fatty acid synthase (FASN) in hepatocellular carcinoma, and further studies found that the ubiquitination of FASN by TRIM21 could be inhibited by glyceronephosphate O-acyltransferase (GNPAT)." (PMID 36694250, 2023). "Targeting NUPR1-SREBP1/FASN pathway may be a therapeutic alternative for hepatocellular carcinoma." (PMID 36307402, 2022). "In the CCl4-induced FAT-NASH mouse model, FASN inhibition decreased hepatic fibrosis and fibrosis markers, and development of hepatocellular carcinoma (HCC) tumors by 85%." (PMID 36123383, 2022). "The inhibition of FASN expression abolished the invasion and migration of HCC cells, demonstrating the contribution of FASN to malignant hepatocellular carcinoma metastasis." (PMID 34150624, 2021). "Although the suppressing effects of celastrol on hepatocellular carcinoma (HCC) have been demonstrated, evidence for the targeting of fatty acid synthetase (FASN) in the development of HCC by celastrol is still rare." (PMID 35539339, 2018). "USP22 deubiquitinates and enhances the stability of PPARγ protein, thereby promoting the synthesis of FASN, ACLY, and ACACA, and facilitating the malignant progression of hepatocellular carcinoma." (PMID 39944823, 2025). "Paradoxically, in sorafenib-resistant hepatocellular carcinoma (HCC) models, FASN orchestrates nuclear accumulation of HIF1α to drive SLC7A11 transactivation, thereby conferring ferroptosis resistance." (PMID 40890129, 2025). "SREBP1c transactivation elevates FASN/ACC expression, propelling hepatocellular carcinoma progression and metastasis." (PMID 41179299, 2025). "For instance, OGT enhances the PI3K/AKT/mTOR signaling pathway by modifying fatty acid synthase (FASN), which promotes hepatoma cell proliferation." (PMID 39487556, 2024). "ZDHHC3 exacerbates the development of nonalcoholic steatohepatitis (NASH) and the progression of hepatocellular carcinoma (HCC) associated to NASH by boosting the accumulation of lipids regulated by IRHOM2 and the production of lipids mediated by FASN signaling." (PMID 39148124, 2024). "In ACI-T mice implanted with subcutaneous hepatoma 3924A cells, a diet high in 10% ALA for 28 days significantly suppressed the expression of fatty acid synthase and promoted death in tumor tissues." (PMID 38068849, 2023). "miR-449 can inhibit SIRT1-SREBP signaling by reducing the expression of SIRT1, SREBP1c, and its downstream genes FASN and HMGCR, thereby controlling adipogenesis and cholesterol production in hepatoma cells." (PMID 36969840, 2023). "In hepatocellular carcinoma HepG2 cells, EGCG simultaneously decreased FASN and ACC protein levels and reduced the activity of CPT1, which was associated with apoptosis." (PMID 38001865, 2023). "FASN has been previously reported to promote carcinogenesis by activating mTOR, a master negative regulator of autophagy, via AKT signaling in hepatocellular carcinoma." (PMID 33742137, 2021).
hepatocellular carcinoma (continued). "We have therefore compared the protein levels of the lipogenic enzyme fatty acid synthase (FAS), in primary hepatocytes with the one of the three hepatoma cell types, in three independent experiments each one with three replicates." (PMID 32694512, 2020). "Our results corroborated these findings in hepatocellular carcinoma model and notably, we also found a strong positive correlation between the SHH expression and the expression of E2F1, FASN, and SREBP1c." (PMID 32577158, 2020). "In hepatocellular carcinoma, acetylation by histone K (lysine) acetyltransferase 8 (KAT8) destabilizes FASN by allowing FASN to interact with TRIM21 E3 ubiquitin-protein ligase for proteasomal degradation." (PMID 32872164, 2020). "A previous study found that miR-27a regulated many lipid metabolism-related transcription factors, including RXRα, PPARγ, FASN, SREBP1, and SREBP2 in human hepatoma cells." (PMID 29445089, 2018). "In hepatocellular carcinoma (HCC), miR-1207-5p inhibits HCC cell growth and invasion by suppressing the AKT/mTOR signaling pathway through fatty acid synthase inhibition." (PMID 30464258, 2018). "Since increased de novo lipogenesis is a characteristic of nonalcoholic fatty liver disease (NAFLD) and hepatocellular carcinoma (HCC), we investigated the liver‐specific genes co‐expressed with fatty acid synthase (FASN)." (PMID 28827398, 2017). "More importantly, human hepatocellular carcinoma with high ACSS1/2 expression exhibit increased histone H3 acetylation and FASN expression." (PMID 27357947, 2016). "MIR-27a was described to be involved in lipid metabolism, by regulating RXRα, PPARα/γ, FASN, SREBP1, SREBP2, and was able to inhibit HCV replication in human hepatoma cells." (PMID 26728044, 2016). "HCV NS4B has been found to enhance the protein expression levels of SREBPs and fatty acid synthase through PI3K activity, subsequently inducing a lipid accumulation in hepatoma cells." (PMID 22922731, 2012). "In addition, USP30 deubiquitinates and stabilizes ACLY and FASN and is overexpressed in the high-fat diet (HFD)-induced hepatocellular carcinoma (HCC)." (PMID 37176148, 2023). "In addition to activating SREBP1, MYC directly regulates the expression of key enzymes involved in FA synthesis, such as ACLY, ACC, FASN, and SCD1, which have been shown to drive tumorigenesis in hepatocellular carcinoma (HCC)." (PMID 37700339, 2023). "In addition, FAO cells (rat hepatocellular carcinoma cells) treated with OA induction also showed decreased gene expression of SREBP-1c, HMGCR, FASN, and ACC." (PMID 37764494, 2023). "In hepatocellular carcinoma and in gastric cancer MACC1 expression positively correlates with expression of 6-phosphofructo-2-kinase/fructose-2,6-bisphosphatase (PFKFB2) and of fatty acid synthase (FASN)." (PMID 33652667, 2021). "Pu-erh tea inhibited the activity of fatty acid synthase (FASN) and acetyl-coenzyme A carboxylase (ACC), key enzymes for lipogenesis and long-chain FA synthesis, in human hepatoma HepG2 cells and rats fed a high-fructose diet and white adipose tissue of ICR mice." (PMID 30804786, 2019). "Fatty acid synthase (FASN), ACC1, ACC2, and carnitine palmitoyl transferase 1 (CPT1) mRNA expression increased after treatment with T in a dose-dependent manner in C3A human hepatoma cells." (PMID 25974403, 2015). "The increase in SREBP1 subsequently upregulated the expression of lipogenic genes, that is, fatty acid synthase (FASN) and acetyl-CoA carboxylase 1 (ACC1), thereby fostering deleterious lipid accumulation in the hepatocellular carcinoma (HCC) cells." (PMID 39990657, 2025).
hepatocellular carcinoma (continued). "In addition, it has been found that increased ACC expression is accompanied by increased FASN and ACLY expression in prostate and hepatocellular carcinoma 39, indicating that ACC may play a synergistic role with FASN and ACLY to promote tumor growth." (PMID 37497413, 2023). "In addition, our data speak against a major role played by the proteasome system in the regulation of c-Met by FASN, as ubiquitination of c-Met was not increased following FASN silencing in hepatoma cell lines." (PMID 26857837, 2016). "Acetyl-CoA carboxylase (ACC) and fatty acid synthase (FASN) are major lipogenic enzymes in lipid anabolism that were observed to be enhanced by CD147, a transmembrane glycoprotein enriched in sEVs from patients with hepatocellular carcinoma (HCC)." (PMID 37208722, 2023).
colorectal cancer (101 papers, 2008 to 2026). A primary or metastatic malignant neoplasm that affects the colon or rectum. "FBXW7β suppresses colorectal cancer by reducing FASN, lipid accumulation, and tumor growth; its loss promotes FASN stability and tumor progression." (PMID 41373479, 2025). "FASN is dysregulated in a variety of cancers, including kidney, liver, lung, and colorectal cancer, and this dysregulation is thought to be associated with the aggressiveness and poor prognosis of cancers." (PMID 36568252, 2022). "On the one hand, the metabolic differences manifested that lipid metabolism was evident in MSI tissues as the fatty acid synthase (FASN) increased in colorectal cancer is associated with MSI." (PMID 32850385, 2020). "Elevated expression of FASN is associated with advanced stage colorectal cancer and colon cancer metastasis." (PMID 29100311, 2017). "However, further studies are needed to explore the underlying mechanisms of FASN in colorectal cancer development and progression." (PMID 40995612, 2025). "In colorectal cancer, cancer-associated fibroblasts underwent lipidomic reprogramming (among others, FASN overexpression) and secreted lipid metabolites for cancer cells; in this study, the uptake of secreted lipids was followed by enhanced migration of colorectal cancer cells." (PMID 36010906, 2022). "Some more recent studies also suggest that FASN might play a role in promoting cellular migration, where reduced expression of FASN has been associated with impaired cell migration in prostate and colorectal cancer cells." (PMID 32139877, 2020). "Additionally, it also suggests that FASN is not only associated with various signaling pathways regulating proliferation, metabolism and survival in colorectal cancer cells, but also controls genes inducing malignant transformation in colorectal oncogenesis." (PMID 23725225, 2013). "An inverse expression of FASN expression with Hakai expression was detected in inflammatory AOM/DSS compared to tumour tissue of colitis-associated colorectal cancer and healthy tissues further suggesting that Hakai may regulate FASN expression in mouse model of inflammatory bowel disease." (PMID 36266428, 2022). "The ROS-mediated inhibition of USP22 is relieved, leading to the stabilization of FASN, thereby promoting lipid synthesis and colorectal cancer growth." (PMID 39944823, 2025). "Research has shown that the stage of colorectal cancer is positively correlated with high expression of FASN, and the high expression of FASN promotes glycolysis and fatty acid oxidation in colorectal cancer cells." (PMID 41488637, 2025). "Upregulation of fatty acid synthase expression increases O-GlcNAc protein glycosylation and promotes colorectal cancer growth." (PMID 39901036, 2025). "Dysregulated fatty acid synthesis is regarded as an important therapeutic target in colorectal cancer, and FASN functions as an enzyme for de novo synthesis." (PMID 40995612, 2025). "Preclinical study of FASN inhibitors in primary colon cancer cells and in a patient‐derived xenograft model of colorectal cancer also demonstrated potent anti‐tumour activity by suppressing the activation of different oncogenic pathways." (PMID 40621620, 2025). "For example, FBXW7β acts as an E3 ligase of FASN, inhibiting colorectal cancer growth by degrading FASN." (PMID 40890129, 2025). "Consistent with previous studies, our data showed that FASN is overexpressed in colorectal cancer tissues." (PMID 40995612, 2025). "For example, the FASN inhibitor TVB-3664 has shown significant anti-cancer activity in colorectal cancer models, an effect correlated with the upregulation of CD36, suggesting a compensatory mechanism involving increased fatty acid uptake." (PMID 41212437, 2025).